ESRP1 (epithelial splicing regulatory protein 1)
Diseases named in the same sentence as ESRP1 in open-access papers (continued):
Sharing a sentence is not in itself a finding about the gene and the disease.
renal aplasia (1 paper, 2016). "First, we discovered a significantly increased risk of unilateral (and rarely bilateral) renal aplasia in many Esrp1‐null mice." (PMID 27404344, 2016). "Ablation of Esrp1 in mice, alone or together with its paralog Esrp2, was associated with reduced kidney size and increased incidence of renal aplasia." (PMID 27404344, 2016). "Taken together with the increased incidence of renal aplasia in Esrp1‐null mice, these findings suggest that Esrp1 is critical for Fgfr2 splicing in the ureteric epithelium to maintain ureteric epithelial architecture." (PMID 27404344, 2016). "The reduced kidney sizes and partially penetrant renal aplasia in Esrp1‐null mutants strongly suggest that alterations in the expression or splicing of Esrp1‐regulated targets lead to these kidney defects." (PMID 27404344, 2016). "First, unlike in the Esrp1 mutants, we did not routinely observe renal aplasia (suggesting ureteric induction defects)." (PMID 27404344, 2016).
renal cell carcinoma (1 paper, 2025). "In this study, we found that the epithelial splicing regulatory protein 1 (ESRP1) was underexpressed in renal cell carcinoma (RCC) cells." (PMID 40866976, 2025). "In this context, this study first investigated ESRP1 expression and promoter methylation status in renal cell carcinoma (RCC) cells, exploring its inhibitory role in RCC proliferation and the underlying mechanisms." (PMID 40866976, 2025).
seminoma (1 paper, 2018). A radiosensitive malignant germ cell tumor found in the testis (especially undescended), and extragonadal sites (anterior mediastinum and pineal gland). "RNA interference mediated knockdown of Esrp1 expression in the seminoma-derived Tcam-2 cell line demonstrated that ESRP1 regulates alternative splicing of mRNAs in a non-epithelial cell germ cell tumour cell line." (PMID 29324788, 2018). "To investigate if ESRP1 can modulate splicing of target genes in fetal germ cells we examined the effects of siRNA knockdown of ESRP1 in vitro, using the seminoma-derived TCam-2 cell line, which has been shown to have characteristics of fetal germ cells." (PMID 29324788, 2018).
teratoma (1 paper, 2013). A non-seminomatous germ cell tumor characterized by the presence of various tissues which correspond to the different germinal layers (endoderm, mesoderm, and ectoderm). "In order to test whether the delay in differentiation was temporal or absolute, in vivo teratoma assay was performed by injecting 3.5×105 Esrp1-depleted cells in NOD-SCID-Gamma (NSG) mice." (PMID 24015231, 2013).
uterine carcinosarcoma (1 paper, 2017). A usually aggressive malignant neoplasm arising from the uterine corpus and less often the cervix. "We then analyzed the frequency of genetic alteration of ESRP1 in various human cancers, and found that ESRP1 gene amplification was common in female cancers including uterine carcinosarcoma, breast and OC." (PMID 28991261, 2017).
Wilms tumor (1 paper, 2022). An embryonal neoplasm characterized by the presence of epithelial, mesenchymal, and blastema components. "We found that ESRP1 and ESRP2 are over-expressed in hFK3 with respect to hFK1 (as well as the Wilms’ tumor xenografts WT37, WT14, and WT11)." (PMID 36380228, 2022). "This might also explain the heterogeneity in expression levels of QKI, and also the fact that unlike ESRP1 and ESRP2, the expression levels of RBFOX2 in the Wilms’ tumor xenograft samples are heterogeneous and not similar to those in hFK1." (PMID 36380228, 2022).
cancer (82 papers, 2012 to 2026). A tumor composed of atypical neoplastic, often pleomorphic cells that invade other tissues. "While CD44 isoform usage and epithelial splicing regulators ESRP1/2 are well-characterized in cancer-associated epithelial-mesenchymal transition (EMT), their regulation across physiological, non-transformed identity states remains less well defined." (PMID 41751394, 2026). "They showed that ESRP1 overexpression enhances cancer cell proliferation and is associated with poor prognosis in BC patients, whereas ESRP2 is not." (PMID 40046628, 2025). "Esrp1/2 exert an epithelial-specific splicing program that is reverted upon initiation of EMT, and Esrp1/2 are implicated in developmental processes and organogenesis, as well as cancer progression." (PMID 41111330, 2025). "A novel role of ESRP1 in cancer progression through posttranscriptional regulation of cancer-associated genes has also been reported." (PMID 38110955, 2023). "In ERG-negative cancers these statistically significant associations were retained for ESRP1 in 8 and for ESRP2 in 9 chromosomal regions." (PMID 33339518, 2020). "The association between ESRP1 expression and tumor progression has been demonstrated in many cancers including PC." (PMID 33194621, 2020). "The higher ESRP1 expression appeared increased risk of disease progression and cancer-specific death in PC." (PMID 33194621, 2020). "ESRP1 induces E-cadherin expression and low levels of ESRP1 are typically associated with a mesenchymal phenotype in cancer cells." (PMID 27119231, 2016). "This truncated ESRP1 transcript variant was found apparently melanocytic specific and the presence in other types of cancer including colon was rare." (PMID 27650542, 2016). "Notably, the ESRP1 low subgroup exhibited substantial enrichment of immunosuppressive elements including cancer-associated fibroblasts (CAFs), macrophages, myeloid-derived suppressor cells (MDSCs), and regulatory T cells (Tregs)." (PMID 40528239, 2025). "Modulating the splicing of CD44 could inhibit tumor invasion and metastasis, making ESRP1 or specific CD44 splice variants potential targets for cancer therapy." (PMID 40046628, 2025). "Despite the prognostic significance and role in some cancers, the role and underlying mechanism of ESRP1 in cancer progression remain unclear." (PMID 38110955, 2023). "Apart from ESRP1, several proteins of the spliceosome have been implicated in cancer development." (PMID 31963158, 2020). "As poorly differentiated tumors have a higher proliferation rate than do well-differentiated tumors, we hypothesized that ESRP1 may be associated with malignant tumor cell proliferation." (PMID 31362365, 2019). "Indirect evidence that RAC1B is involved in regulating cell motility already came from the EMT-promoting role of RAC1B (see Section 5.4) and from a study showing that downregulation of the splicing factor ESRP1 is closely associated with a motile phenotype of cancer cells and induction of RAC1B." (PMID 30621237, 2019). "In line with this hypothesis, the EMT-TF ZEB1, which is upregulated in several human cancers, directly inhibits ESRP1 expression, thus causing AS changes in the CD44 gene." (PMID 28137272, 2017). "One gene was ESRP1, which has been found to be associated with Pinin in a previous study and whose expression was significantly upregulated in Pinin-KD and CtBP1-KD cancer cells in the present study." (PMID 26871283, 2016). "Importantly, the expression of ESRP1 was associated with response to immunotherapy in cancer." (PMID 38110955, 2023). "In other cancer types, elevated ESRP1 has correlated with less aggressive behavior and favorable prognosis." (PMID 41155518, 2025). "When correlating PSI values of each ASE with expression of ESRP1 in cancer cells, we found that 74 ASEs correlated significantly (FDR < 0.05)." (PMID 41273175, 2025). "Taken together, these observations support a role for ESRP1 in determining AS differences between cancer cells from Es versus NEs." (PMID 41273175, 2025).
cancer (continued). "More and more evidence suggests that the dysregulation of ESRP1 is closely related to cancer progression, providing a new entry point for the treatment of cancer patients based on ESRP1 dysregulation." (PMID 40046628, 2025). "Studies have reported that ESRP1 plays a crucial role in suppressing tumorigenic potential and/or attenuating metastasis in various types of cancer." (PMID 40528239, 2025). "Epithelial splicing regulatory protein 1 (ESRP1), an RNA‐binding protein that regulates mRNA splicing, is partially responsible for the chemoresistance of various cancers, including NSCLC." (PMID 39083441, 2025). "This review primarily discusses the molecular mechanisms of ESRP1 in regulating cancer metastasis, particularly its regulatory effects on CD44 splicing and the EMT process." (PMID 40046628, 2025). "Since the shift in CD44 isoforms is essential for EMT and ESRP1 is a master SF in EMT, it is plausible that CD44s and the depletion of ESRP1 represent a common pathway in the EMT process in cancer." (PMID 40538061, 2025). "ESRP1 is actively involved in cancer progression by mediating the EMT process and ESRP1-related regulatory loops were well depicted." (PMID 39550559, 2024). "As is expected, ESRP1 also orchestrates AS events in multiple cancer types and is suggested as a tumor-suppressive splicing factor that represses EMT to restrain malignancy." (PMID 39550559, 2024). "cESRP1, which is derived from the epithelial splicing regulatory protein 1 (ESRP1) gene, has been linked to several biological processes, including the regulation of the EMT and the advancement of cancer." (PMID 38505309, 2024). "We hope that this study sets the stage for a more complete understanding of ACLY splicing and the role of ESRP1 in cancer." (PMID 38815867, 2024). "Further efforts to increase understanding on the roles and mechanism of ESRP1 in tumorigenesis are necessary for targeting ESRP1 for cancer therapy." (PMID 38110955, 2023). "Given that EMT is involved in drug resistance by generating cancer stem cells or tumor-initiating cells, ESRP1 is expected to play a role in response to anticancer drugs and stemness." (PMID 38110955, 2023). "In line with the role of ESRP1 in EMT, its high expression is associated with favorable prognosis in some cancers." (PMID 38110955, 2023). "Taken together, these results indicate that multiple factors, including TME, epigenetic mechanisms, and transcription factors, together play a role in ESRP1 regulation during cancer progression." (PMID 38110955, 2023). "Supporting this, several studies indicate that ESRP1 overexpression plays a crucial role in various cancers where they also correlate with poorer survival statistics." (PMID 37752235, 2023). "This review summarizes the current understanding of the roles and mechanisms of ESRP1 in cancer progression, and further discusses the emerging novel roles of ESRP1 in cancer and recent attempts to target splicing factors for cancer therapy." (PMID 38110955, 2023). "Various epithelial markers including epithelial cell adhesion molecule (EpCAM), cadherin 1 (Cdh1), keratin (Krt) 5/14, desmoglein 2 (Dsg2), and epithelial splicing regulatory protein 1/2 (Esrp1/2) have been adopted to depict the EMT states of cancers." (PMID 37654227, 2023). "This review describes current understanding of the roles and mechanisms of ESRP1 in cancer progression, and further discusses the emerging novel roles of ESRP1 in cancer and recent attempts to target splicing factors for cancer therapy." (PMID 38110955, 2023). "Studies have revealed that ESRP1 regulates epithelial- and mesenchymal-specific isoforms that have important roles in EMTs and disease processes such as cancer metastasis." (PMID 36307405, 2022). "When ZEB1/2 were upregulated and maintained at high levels in aggressive cancer cells, the IIIc isoforms of FGFRs were expressed through isoform switching when ESRP1/2 expression was repressed." (PMID 36140527, 2022).
cancer (continued). "As in the previous studies about ESRP1 in other cancers, high expression of ESRP1 showed longer overall survival times 11,12." (PMID 36307405, 2022). "Remarkably, an increasing number of studies has unveiled a central role of Epithelial Splicing Regulatory Protein 1 (ESRP1) in fine-tuning RNA metabolism at different stages of cancer progression." (PMID 34362878, 2021). "Intriguingly, our data show, unprecedently that ESRP1 promotes the expression of and involves RAC1b in its cancer-promoting role." (PMID 34439247, 2021). "ZEB1 drives EMT and confers chemotherapeutic resistance of cancer cells via directly altering the expression of a plethora of genes, like ESRP1 and ATM25,26." (PMID 33542225, 2021). "Dysregulation of EMT events through the overexpression of ESRP1 in particular, has dire consequences for cell differentiation and consequently is typically observed in many types of cancers." (PMID 34769047, 2021). "A decrease in two proteins was significant in this cell line following the expression in ESRP1 including phosphoglycerate kinase 1 (PGK1) a prognostic biomarker for cancer." (PMID 31963158, 2020). "A tissue microarray made from 17,747 individual cancer samples with comprehensive, pathological, clinical and molecular data was analyzed by immunohistochemistry for ESRP1 and ESRP2." (PMID 33339518, 2020). "In ERG-positive cancers, a statistically significant difference was found for ESRP1 in 5 and for ESRP2 in 1 of the analyzed loci." (PMID 33339518, 2020). "Functional network analysis suggested that ESRP1 regulated ribosome metabolism, drug metabolism, and chemical carcinogenesis via pathways involving several cancer-related kinases, miRNAs, and transcription factors." (PMID 32964032, 2020). "Epithelial splicing regulatory protein 1 (ESRP1) has been described as an RNA-binding protein involved in cancer development." (PMID 32964032, 2020). "Expression of ESRPs was significantly linked to 11 (ESRP1)/9 (ESRP2) of 11 analyzed deletions in all cancers and to 8 (ESRP1)/9 (ESRP2) of 11 deletions in ERG-negative cancers portending a link to genomic instability." (PMID 33339518, 2020). "Combined ESRPs expression analysis suggested an additive effect and showed the worst prognosis for cancers with high ESRP1 and ESRP2 expression." (PMID 33339518, 2020). "By contrast, ectopic overexpression of ESRP1 seems to promote the switch from a mesenchymal to an epithelial cancer cell phenotype 51." (PMID 32685007, 2020). "Nuclear staining for ESRP1 was seen in 38.6% (36.0% low, 2.6% high) of 12,140 interpretable cancers and in 41.9% (36.4% low, 5.3% high) of 12,962 interpretable cancers for ESRP2." (PMID 33339518, 2020). "CCAR2, found on human chromosome 8 (8p21.3), is involved in multiple cellular processes, and like ESRP1, it has a dual role in cancer depending on the context." (PMID 31963158, 2020). "In contrast, careful analysis revealed a loss of ESRP1 and ESRP2 expression in cancer cells that penetrated through the basement membrane into the stroma as well as in those cells that invaded from cancer nests into stromal tissues." (PMID 32957697, 2020). "While RBFOX3, RBM11 (RNA binding motif protein 11) and DDX25 (DEAD-box helicase 25) are generally downregulated in cancers compared to normal cells, the dysregulation of CELF5, ELAVL2 and ESRP1 is dependant on the type of cancer." (PMID 30704403, 2019). "High levels of ESRP1 protein have previously been observed in well-to-moderately differentiated cancer cells, whereas this expression was markedly reduced when cells were instead poorly-differentiated." (PMID 31362365, 2019). "ESRP1 is a tumor suppressor in CRC due to their ability to regulate translation of several cancer-related genes by binding to their mRNA 5′UTRs." (PMID 31440515, 2019). "On the basis of this and findings by others, we conclude that MA cells express a high ZEB1/low ESRP1/high CD44s network that enforces self-renewal in cancer stem–like cells." (PMID 31217902, 2019).
cancer (continued). "The regulation of p120 isoform expression, for instance through ESRP1 and 245, and the functional significance of p120-3 and p120-1 expression in development and cancer warrants further work." (PMID 30643202, 2019). "In another study, ESRP1 was also found to enhance lung colonization of metastatic cancer cells, thus supporting a pro-metastatic function for ESRPs." (PMID 29401653, 2018). "Consistently, analysis of cancer genome atlas (TCGA) data from 450 human CRC samples revealed that ESRP1 expression was extremely heterogeneous, with RNA-Seq by Expectation Maximization (RSEM) values ranging from below 200 to over 8000." (PMID 28052020, 2017). "We also performed a tissue microarray (TMA) based analysis of matched intestinal tissues from a cohort of 185 CRC patients, which revealed a gradual decrease in nuclear expression of ESRP1 protein during cancer progression." (PMID 28975893, 2017). "In accordance to the observation in cancer cells with ESRP1 overexpression and knockdown, V6 and V7 shRNAs significantly reduced MCF10CA1a invasion in the presence of OPN." (PMID 28300837, 2017). "Down-regulation of ESRP1 and ESRP2 has also been closely associated with a motile phenotype of cancer cells." (PMID 27565572, 2016). "ESRP1 has been shown to affect the mRNA translation of several cancer-related genes, including c-Myc and Fos, through direct binding of their 5′ untranslated regions (UTRs)." (PMID 24015231, 2013). "Further research on the relationship and mechanisms of action between ESRP1 and CD44 in cancer could lead to the development of new diagnostic markers and treatment targets." (PMID 40046628, 2025). "While ESRP1 inhibits invasion and metastasis in some cancers, it may promote disease progression in others." (PMID 40046628, 2025). "In addition, the differential expression of ESRP1 across tumor types suggests that its therapeutic potential is likely to be study-specific, requiring tailored approaches for specific cancer types." (PMID 40046628, 2025). "Therefore, further research on the specific role of ESRP1 in ccRCC and the feasibility of its targeted strategies will help reveal the pathogenesis of ccRCC and provide new insights for personalized cancer therapy." (PMID 40046628, 2025). "ESRP1 exhibits both anti-cancer and pro-cancer effects in different cancer types." (PMID 40046628, 2025). "Therefore, given ESRP1’s critical role in cancer development, it is gradually becoming a potential biomarker and therapeutic target." (PMID 40046628, 2025). "On the other hand, even for splicing factors with clear functional relevance, such as QKI and ESRP1, target genes of the same splicing factor may impose opposite effects on cancers in a context-dependent manner." (PMID 39550559, 2024). "Additional studies are warranted to validate whether ESRP1 is suitable as a therapeutic target for cancer therapy or potential biomarker for prognosis or predicting response to anticancer drugs." (PMID 38110955, 2023). "Furthermore, recent studies have demonstrated that ESRP1 is involved in cancer progression by regulating cellular metabolism or immune cell infiltration in the TME, indicating the novel roles of ESRP1 in addition to EMT." (PMID 38110955, 2023). "However, recent studies have demonstrated the mechanisms upregulating ESRP1 expression in cancer cells." (PMID 38110955, 2023). "However, there are reports of genetic defects in ESRP genes in human cancers, specifically, microsatellite indels or duplications of ESRP1." (PMID 34520622, 2022). "Cancer cells with high levels of ZEB1/2 show low levels of ESRP1/2 and high levels of CD44s." (PMID 36140527, 2022). "ESRP1 is closely related to the poor prognosis of cancer patients, because ESRP1 can directly bind to the GGT-rich sequence to cut the circRNA, thereby accelerating the circRNA (such as circUHRF1 and circANKS1B) biogenesis, which in turn promotes tumor growth and metastasis." (PMID 34439339, 2021).